ZFC3H1 (zinc finger C3H1-type containing)
Description:
Subunit of the trimeric poly(A) tail exosome targeting (PAXT) complex, a complex that directs a subset of long and polyadenylated poly(A) RNAs for exosomal degradation. The RNA exosome is fundamental for the degradation of RNA in eukaryotic nuclei. Substrate targeting is facilitated by its cofactor MTREX, which links to RNA-binding protein adapters.
Synonyms: CCDC131; KIAA0546; PSRC2; MGC23401; CSRC2
Tractability: PROTAC: ubiquitination databases record sites on it; its protein half-life has been measured.
Gene: Protein-coding gene on chromosome 12 (71,609,599 to 71,667,725, reverse strand). Ensembl gene ENSG00000133858.
Subcellular location: Nucleus
Subcellular location (Human Protein Atlas): Nucleoplasm; Intermediate filaments
Pathways (Reactome):
Metabolism of RNA: Nuclear RNA decay
Gene Ontology:
Molecular function: protein binding
Biological process: RNA catabolic process; RNA processing
Cellular component: extracellular region; MTREC complex; nucleolus; nucleus; nucleoplasm
Genetic constraint (gnomAD): Loss-of-function variants: 69 observed, 229.9 expected, observed/expected ratio (o/e) 0.3, 90% interval 0.25 to 0.37. The upper end of that interval is the gene's LOEUF score, 0.37, which puts it in group 1 of 6, group 1 being the genes least tolerant of losing a copy. Missense variants: 1,909 observed, 2,324.5 expected, observed/expected ratio (o/e) 0.82, 90% interval 0.79 to 0.85. Synonymous variants: 814 observed, 818.33 expected, observed/expected ratio (o/e) 0.99, 90% interval 0.94 to 1.05.
Homologues: Orthologues: chimpanzee ZFC3H1 (99% identical), macaque ZFC3H1 (99% identical), rabbit ZFC3H1 (95% identical), pig ZFC3H1 (95% identical), rat Zfc3h1 (92% identical), guinea pig ZFC3H1 (92% identical), mouse Zfc3h1 (92% identical), dog ZFC3H1 (89% identical), tropical clawed frog zfc3h1 (57% identical).
Diseases named in the same sentence as ZFC3H1 in open-access papers:
ZFC3H1 is named in the same sentence as 24 diseases in open-access papers, as found by Europe PMC text mining. Sharing a sentence is not in itself a finding about the gene and the disease. The quoted sentences say what the papers report.
prostate adenocarcinoma (2 papers, 2021 to 2022). "The results showed that the expression levels of ZFC3H1 were notably lower than the corresponding non-cancerous tissues in prostate adenocarcinoma (PRAD), and patients in the high ZFC3H1-expression group showed poor survival." (PMID 34514952, 2021).
prostate carcinoma (2 papers, 2021 to 2022). A carcinoma that arises from epithelial cells of the prostate gland. "The authors also report that the knock-down of ZFC3H1 in prostate cancer cell lines 22RV1, and DU145 lead to the inhibition of cell migration and invasion, and reduces cell viability while increasing apoptosis." (PMID 36551962, 2022). "We also detected ZFC3H1 expression in 10 prostate cancer specimens and paracancerous, by immunohistochemical staining which indicated that the ZFC3H1 expression was down-regulated in tumors when compared with Normal." (PMID 34514952, 2021).
lung carcinoma (1 paper, 2014). "The knockdown of ZFC3H1 reduced IL-8 expression levels in the TNFα-stimulated lung carcinoma cell line, LU99, and UV-irradiated HeLa cells." (PMID 25268596, 2014).
pulmonary hypertension (1 paper, 2023). Increased pressure within the pulmonary circulation due to lung or heart disorder. "ZFC3H1 promotes the expression of BRD4 and HIF1a in PASMC, and its inhibition leads to the down-regulation of BRD4 and HIF1a and the reversal of the PAH phenotype in a murine model of pulmonary hypertension." (PMID 38132114, 2023).
cancer (3 papers, 2020 to 2022). A tumor composed of atypical neoplastic, often pleomorphic cells that invade other tissues. "First, we found that ZFC3H1 expression levels in many cancers, including PRAD, were significantly lower compared with those in corresponding non-cancerous tissues." (PMID 34514952, 2021). "In addition, ZFC3H1 was amplified at a high level above 5% in only two cancer types, ACC and SARC." (PMID 35008922, 2022).
tumor (3 papers, 2014 to 2022). "We hypothesized that the low expression of ZFC3H1 in tumor tissue might have be an inhibitory effect on the autoimmune system." (PMID 34514952, 2021). "Although we did not focus on the detailed molecular mechanisms of Celastramycin A in the tumor-bearing model mouse system, ZFC3H1 may be a target molecule for the prevention of tumor metastasis." (PMID 25268596, 2014).
infection (1 paper, 2018). The state of being infected such as from the introduction of a foreign agent such as serum, vaccine, antigenic substance or organism. "At 3 days post-infection, cells were transduced with lentiviral particles expressing shRNAs targeting MTR4, ZFC3H1+ZCCHC8 or a negative control shRNA." (PMID 29554134, 2018).
ZFC3H1 also shares sentences with these, for which no sentence is quoted: adrenocortical carcinoma (1 paper); cervical squamous cell carcinoma (1); colon adenocarcinoma (1); colorectal tumor (1); endocervical adenocarcinoma (1); hepatocellular carcinoma (1); liver fibrosis (1); lung adenocarcinoma (1); lung squamous cell carcinoma (1); ovarian serous cystadenocarcinoma (1); rectum adenocarcinoma (1); skin cutaneous melanoma (1); testicular germ cell tumor (1); thymoma (1); thyroid carcinoma (1); uterine carcinosarcoma (1); uterine corpus endometrial carcinoma (1).